SAMD8 (sterile alpha motif domain containing 8)
Description:
Has phospholipase C (PLC) activity. Shows specificity for phosphatidylethanolamine (1,2-diacyl-sn-glycero-3-phosphoethanolamine, PE), hydrolyzing PE to produce phosphoethanolamine and diacylglycerol (1,2-diacyl-sn-glycerol, DAG). This reaction might act as a regulatory switch to activate serine palmitoyltransferase (SPT) and promote sphingolipid metabolism (By similarity). Can also function as a ceramide phosphoethanolamine (N-acylsphingoid 1-phosphoethanolamine, CPE) synthase when intracellular ceramide levels are elevated. Binds the headgroup from PE, which is smaller and more hydrophilic than the phosphocholine headgroup transferred in the canonical sphingomyelin synthesis (SMS) reaction by SMS1 or SMS2, and transfers it on to the primary hydroxyl of a ceramide in the lumen of the endoplasmic reticulum. Plays a role as a ceramide sensor, helping to regulate ceramide homeostasis in the endoplasmic reticulum, which is critical for maintaining the integrity of the early secretory pathway.
Synonyms: SMSr; PE-PLC; FLJ25082; HEL-177
Tractability: Small molecule: a structure with a bound ligand is known. Antibody: UniProt predicts a signal peptide or a membrane-spanning region; its Gene Ontology location is reachable by antibodies, with medium confidence. PROTAC: ubiquitination databases record sites on it; its protein half-life has been measured.
Gene: Protein-coding gene on chromosome 10 (75,099,586 to 75,182,127, forward strand). Ensembl gene ENSG00000156671.
Subcellular location: Endoplasmic reticulum membrane
Subcellular location (Human Protein Atlas): Cytosol; Endoplasmic reticulum
Pathways (Reactome):
Metabolism: Sphingolipid de novo biosynthesis
Gene Ontology:
Molecular function: ceramide cholinephosphotransferase activity; sphingomyelin synthase activity; ceramide phosphoethanolamine synthase activity; phosphotransferase activity, for other substituted phosphate groups
Biological process: ceramide biosynthetic process; regulation of ceramide biosynthetic process; sphingomyelin biosynthetic process
Cellular component: endoplasmic reticulum; endoplasmic reticulum membrane; Golgi membrane; membrane; plasma membrane
Genetic constraint (gnomAD): Loss-of-function variants: 17 observed, 35.72 expected, observed/expected ratio (o/e) 0.48, 90% interval 0.32 to 0.71. The upper end of that interval is the gene's LOEUF score, 0.71, which puts it in group 2 of 6, group 1 being the genes least tolerant of losing a copy. Missense variants: 310 observed, 499.22 expected, observed/expected ratio (o/e) 0.62, 90% interval 0.56 to 0.68. Synonymous variants: 153 observed, 170.21 expected, observed/expected ratio (o/e) 0.9, 90% interval 0.79 to 1.03.
Homologues: Orthologues: chimpanzee SAMD8 (100% identical), macaque SAMD8 (99% identical), dog SAMD8 (98% identical), pig SAMD8 (98% identical), rabbit SAMD8 (98% identical), guinea pig SAMD8 (96% identical), mouse Samd8 (96% identical), rat Samd8 (94% identical), tropical clawed frog samd8 (82% identical), Drosophila melanogaster SMSr (52% identical), Caenorhabditis elegans F53B1.2 (46% identical). Paralogues in human: SGMS1 (36% identical), SGMS2 (32% identical).
Diseases named in the same sentence as SAMD8 in open-access papers:
SAMD8 is named in the same sentence as 15 diseases in open-access papers, as found by Europe PMC text mining. Sharing a sentence is not in itself a finding about the gene and the disease. The quoted sentences say what the papers report.
glioma (1 paper, 2023). A benign or malignant brain and spinal cord tumor that arises from glial cells (astrocytes, oligodendrocytes, ependymal cells). "we found that SAMD8, RER1, MXI1, and CHI3L1 were highly expressed in most of the glioma tumor microenvironment cells." (PMID 37934565, 2023).
lung carcinoma (1 paper, 2022). "It was determined that the miRNA expression of genes CDK19, SAMD8, TBL1XR1, and TRPS1 were significantly upregulated in the LUSC dataset between lung cancer patients and controls." (PMID 35885958, 2022).
ZIKV infection (1 paper, 2018). "The topological analysis on the extended network identified SH2B adaptor protein 3 (SH2B3), FGFR10P2, ACSL3, OPTN, SAMD8, and TNFRFS13B as additional key molecules associated with ZIKV infection." (PMID 30046058, 2018).
SAMD8 also shares sentences with these, for which no sentence is quoted: fatty liver (2 papers); tumor (2); hyperlipidemia (1); leukemia (1); liver fibrosis (1); metabolic disease (1); neurodegenerative disease (1); neuroendocrine tumor (1); nonalcoholic fatty liver disease (1); nonalcoholic steatohepatitis (1); Obesity (1); type 2 diabetes (1).